GPX4 (glutathione peroxidase 4)
Diseases named in the same sentence as GPX4 in open-access papers (continued):
Sharing a sentence is not in itself a finding about the gene and the disease.
HCMV infection (1 paper, 2025). "This indicates that residual activity of the remaining GPX4 within infected cells during HCMV infection can still likely modulate cell viability, although a direct linkage to ferroptosis has not been established." (PMID 39772623, 2025). "The increase in lipid peroxidation observed during HCMV infection correlates with a decrease in GPX4 expression, which suggests a role for the downregulation of GPX4 in the increase of lipid peroxidation." (PMID 39772623, 2025). "Here, we demonstrate that HCMV infection downregulates the expression of a key modulator of lipid peroxidation, glutathione peroxidase 4 (GPX4)." (PMID 39772623, 2025). "Following HCMV infection, we observed that GPX4 knockdown further increased lipid peroxidation and LDH release but showed a similar decrease in ATP levels to uninfected controls expressing the same shRNA constructs." (PMID 39772623, 2025). "However, the results demonstrate that during HCMV infection, GPX4 can moderately modulate lipid peroxidation and potentially affect the induction of ferroptosis." (PMID 39772623, 2025). "However, further investigation is required to determine the exact mechanisms of GPX4 downregulation during HCMV infection." (PMID 39772623, 2025). "This raised the possibility that an increase in FSP1 production could potentially counteract the effects of a decrease in GPX4 expression during HCMV infection." (PMID 39772623, 2025). "Additionally, GPX4 downregulation occurred as early as 4 hpi in both wild-type and UV-inactivated HCMV infection." (PMID 39772623, 2025). "To investigate whether HCMV infection modulates the activity of the metabolic pathway between system Xc− and GPX4, we sought to explore the effects of erastin and RSL3 on intracellular levels of GSH, the substrate of GPX4 used to reduce lipid peroxides." (PMID 39772623, 2025). "For instance, during HCMV infection, a large decrease in GPX4 expression, aligned with a corresponding increase in lipid peroxidation, could readily lead to the conclusion that HCMV-infected cells are more susceptible to induction of ferroptosis." (PMID 39772623, 2025). "Further intricacy in the lipid peroxidation pathway during HCMV infection was revealed when ferrostatin-1 treatment, but not GPX4 overexpression, reversed HCMV-induced lipid peroxidation." (PMID 39772623, 2025). "We found that GPX4 and FSP1 are differentially regulated during HCMV infection." (PMID 39772623, 2025). "Since infected cells have reduced GPX4 levels, we hypothesized that a reduction in FSP1 levels would induce ferroptosis in infected cells, thus inhibiting HCMV infection." (PMID 39772623, 2025). "As GPX4 overexpression did not reduce lipid peroxidation during HCMV infection, we sought to investigate whether other mechanisms that regulate levels of lipid peroxides impacted HCMV replication or induction of ferroptotic markers." (PMID 39772623, 2025).
Hearing impairment (1 paper, 2024). A decreased magnitude of the sensory perception of sound. "Our study aimed to investigate the role of ferroptosis in sevoflurane-induced hearing impairment and explore the mechanism of the microRNA-182-5p (miR-182-5p)/Glutathione Peroxidase 4 (GPX4) pathway in sevoflurane-induced ototoxicity." (PMID 38928480, 2024).
hepatitis B virus infection (1 paper, 2024). A viral infection caused by the hepatitis B virus. "Last, we determined whether or not GPX4 methylation is associated with hepatitis B virus infection." (PMID 38515187, 2024).
hepatoblastoma (1 paper, 2025). Hepatoblastoma (HB) is a malignant hepatic tumor and is the most common pediatric liver cancer.
HIV-1 infection (1 paper, 2022). The type species of lentivirus and the etiologic agent of acquired immunodeficiency syndrome (AIDS). "We monitored the expression of five selenoproteins, namely GPX4, GPX1, SELENOO, TXNRD1 and SELENOS, in response to HIV-1 infection at various time points and in cellular protein extracts." (PMID 35163318, 2022). "Based on the migration on SDS-PAGE and radioactive signal intensity, it was suggested that TXNRD1, GPX4 and GPX1 were downregulated in Jurkat cells after HIV-1 infection in favor of one or more low-molecular-weight selenocompounds." (PMID 35163318, 2022).
Hyperinsulinemia (1 paper, 2025). An increased concentration of insulin in the blood. "This is exacerbated by NRF2 pathway suppression due to hyperinsulinemia-induced KEAP1 stabilization, which downregulates GPX4 and depletes GSH, rendering HCC cells vulnerable to sorafenib-induced ferroptosis." (PMID 40689204, 2025).
hypersomnia (1 paper, 2023). A sleep disorder characterized by excessive sleepiness. "Six (GPX4, PSMB5, PSMB6, PRDX5, ASNA1, EIF4H) out of seven hub genes were associated with the expression of insomnia/hypersomnia only in females, while UROD was the only hub gene common to both sexes." (PMID 37884562, 2023).
hypopharyngeal carcinoma (1 paper, 2026). Carcinoma, predominantly squamous cell, arising from the epithelial cells of the hypopharynx.
idiopathic pulmonary hypertension (1 paper, 2024). "Furthermore, the results indicated an increase in the expression of DEGs related to the reactive oxygen species pathway (NDUFB4, PDLIM1, GPX4, and JUNB), and a decrease in the expression of SOD, which has an antioxidant function, in the presence of idiopathic pulmonary hypertension." (PMID 38586587, 2024).
IgA nephropathy (1 paper, 2025). "Recent studies have found that GPX4 expression in the kidneys of patients with IgA nephropathy is significantly lower than in healthy controls." (PMID 41425591, 2025). "Mechanistically, the downregulation of peroxisome proliferator-activated receptor α mediates the regulation of fatty acid-binding protein 1 on GPX4 and ACSL4, leading to ferroptosis and promoting the development of IgA nephropathy." (PMID 41425591, 2025).
Immunodeficiency (1 paper, 2021). Failure of the immune system to protect the body adequately from infection, due to the absence or insufficiency of some component process or substance. "To determine if systemic HDL NP treatment reduces GPX4 expression and increases lipid peroxide accumulation in tumor cells in vivo, we established SUDHL4 tumor xenografts (∼100 mm3 in volume) in severe combined immunodeficiency–beige mice." (PMID 33208460, 2021).
intervertebral disc degeneration (1 paper, 2023). "The immunofluorescence results indicate a significant increase in the expression levels of NCOA4 and PCBP1 proteins, while the expression level of GPX4 protein was decreased in human intervertebral disc degeneration tissues." (PMID 37736497, 2023).
intrahepatic cholangiocarcinoma (1 paper, 2025). A carcinoma that arises from the intrahepatic bile duct epithelium in any site of the intrahepatic biliary tree. "PAX8‐AS1 drives chemoresistance in intrahepatic cholangiocarcinoma by activating NRF2‐mediated GPX4 transcription and stabilizing GPX4 mRNA via IGF2BP3." (PMID 40391780, 2025). "Targeting the PAX8‐AS1/GPX4 axis with a GPX4 inhibitor enhances the efficacy of gemcitabine and cisplatin in preclinical models, offering a promising strategy to overcome chemotherapy resistance in advanced intrahepatic cholangiocarcinoma." (PMID 40391780, 2025).
joint diseases (1 paper, 2025). "The connections between ferroptosis and bone and joint diseases involve mainly iron metabolism, ROS, GPX4, and lipid peroxidation processes." (PMID 40740786, 2025).
liver failure (1 paper, 2025). A liver disease characterized by the liver losing or has lost all of its function. "Based on these results and to functionally define the role of GPX4 in hepatocytes in situations leading to liver failure, we generated mice with a hepatocyte‐specific deletion of Gpx4 and used the acute CCl4 model to induce ALF." (PMID 40844245, 2025).
lysosomal storage disease (1 paper, 2021). A metabolic disorder caused by mutations in proteins critical for lysosomal function, including lysosomal enzymes, lysosomal integral membrane proteins, and proteins involved in the post-translational modification and trafficking of lysosomal proteins. "In the context of lysosomal storage diseases, there are few reports of modulation of the GPX4-GSH-Xc− system." (PMID 33578654, 2021).
malnutrition (1 paper, 2021). Inadequate nutrition resulting from poor diet, malabsorption, or abnormal nutrient distribution. "Research has already reported that cells with downregulated GPX4 expression were more sensitive to malnutrition, whereas upregulated GPX4 expression inhibited ferroptosis, indicating that GPX4 plays an important role in ferroptosis." (PMID 34725564, 2021).
metastatic cancer (1 paper, 2022). A carcinoma which has spread from the original site of growth to another anatomic site. "In our RNA-seq data, GPX1 and GPX4 were reduced in neutrophils incubated in metastatic cancer CM, suggesting neutrophils in a metastatic environment cannot regulate H2O2 levels." (PMID 35604506, 2022).
migraine (1 paper, 2024). "Topiramate has been proposed as a migraine preventive medication because it inhibits ferroptosis via the glutathione peroxidase 4 (GPX4), GSH, and cystine/glutamate antiporter (System Xc-)." (PMID 39416954, 2024).
mucous adenocarcinoma (1 paper, 2021). "Therefore, the expression of GPX4 in 32 normal tissues and 33 mucous adenocarcinoma tissues was analyzed in the GEO database (GSE146009)." (PMID 34601499, 2021).
muscular atrophy (1 paper, 2025). The loss of muscle tissue due to inactivity or disease. "In animal models, neuron-specific GPX4 deletion resulted in muscular atrophy, paralysis, and motor neuron degeneration, indicating that GPX4 expression is linked to cell vulnerability in ALS." (PMID 40002678, 2025).
myeloid leukemia (1 paper, 2024). A clonal proliferation of myeloid cells and their precursors in the bone marrow, peripheral blood, and spleen. "The role of GPX4 in the development of the myeloid lineage and in the initiation and progression of myeloid leukemia remains poorly explored." (PMID 38977956, 2024). "Given its essential role in the detoxification of lipid hydroperoxides, and its overexpression in most of myeloid malignancies, GPX4 inhibition has emerged as a promising therapeutic strategy to specifically trigger ferroptosis and eradicate myeloid leukemia cells." (PMID 38977956, 2024). "However, the role of GPX4 in the development of the myeloid lineage and in the initiation and progression of myeloid leukemia remains poorly explored." (PMID 38977956, 2024). "Given its essential role in the detoxification of lipid hydroxy peroxides, and its overexpression in most of myeloid malignancies, GPX4 inhibition has emerged as a promising therapeutic strategy to induce ferroptosis as a mean of eradicating myeloid leukemia cells." (PMID 38977956, 2024).
necrotizing enterocolitis (1 paper, 2025). Necrotizing enterocolitis (NEC) is a devastating disease that affects mostly the intestine of premature infants. "The reduction of Treg cells in necrotizing enterocolitis (NEC) is ascribed to ferroptosis caused by decreased expression of GPX4." (PMID 40534879, 2025).
oropharyngeal cancer (1 paper, 2025). Carcinoma, predominantly squamous cell, arising from the epithelial cells of the oropharynx. "It is confirmed that Stat3 can bind GPX4 promoter region, then regulate GPX4 protein expression in oropharyngeal cancer cell by chromatin immunoprecipitation assay." (PMID 41341590, 2025).
ovarian dysfunction (1 paper, 2023). The inability of the ovaries to function. "Previous studies have reported a correlation between GSH, GPX4 and ovarian dysfunction; however, few studies have focused on the correlation between SLC7A11 and POI43–46." (PMID 36932163, 2023).
Peri-Implantitis (1 paper, 2024). An inflammatory process with loss of supporting bone in the tissues surrounding functioning DENTAL IMPLANTS. "However, in an in vitro peri-implantitis study, lower GPx4 mRNA expression was observed in LPS-induced bone-marrow-derived mesenchymal stem cells (BMSCs) compared to the control group." (PMID 39400614, 2024).
pituitary adenomas (1 paper, 2010). "Moreover, GPX4 (glutathione peroxidase 4) was significantly down-regulated (26-fold) in pituitary adenomas relative to controls." (PMID 20426862, 2010).
Psychosis (1 paper, 2023). "Our results demonstrate an increased presence of iron deposits that are accompanied by a further expression of TFRC, ACSL-4, ALOX-5, MDA, and GPX4—all of which are observed in the placenta tissue of women who have suffered from a first episode of psychosis." (PMID 36671505, 2023). "Finally, we observe an overexpression of GPX4 in the placenta tissue of women who have suffered a first episode of psychosis." (PMID 36671505, 2023).
pulpitis (1 paper, 2025). Inflammation of the dental pulp. "ROS and Fe2+ levels significantly rose, and immunohistochemistry showed low expression of GPX4 and high expression of PTGS2 in pulpitis." (PMID 41087337, 2025). "In rat pulpitis models, both prothymosin α (PTMA, precursor of thymosin α1) gelatin sponge placed at the hole of pulp (LPS-P(gs)) and PTMA injection in pulp (LPS-P(i)) significantly reduced infiltration of inflammatory cells and expression of PTGS2, and increased the expression of GPX4." (PMID 41087337, 2025).
renal medullary carcinoma (1 paper, 2025). "Accordingly, tRCC lines showed marked sensitivity to GPX4 inhibition with IC50 values in the nanomolar range similar to renal medullary carcinoma lines." (PMID 40148585, 2025).
Sjögren’s syndrome (1 paper, 2025). "Downregulation of GPX4 in salivary gland epithelial cells leads to salivary secretion dysfunction in Sjögren’s syndrome via the lipid ROS/pSTAT4/AQP5 axis." (PMID 40934008, 2025). "Melatonin inhibits ferroptosis in salivary gland epithelial cells in primary Sjögren’s syndrome via the NRF2/HO-1/GPX4 signaling pathway, thereby attenuating ferroptosis-triggered NF-κB activation." (PMID 40934008, 2025). "Research has demonstrated that autologous serum from patients with Sjögren’s syndrome alleviates hypertonicity-induced corneal epithelial ferroptosis by inhibiting the Xc/GPX4 pathway." (PMID 40934008, 2025).
skin tumor (1 paper, 2025). "Under the combined action of the TCM β‐elemene (β‐ELE) and NIR light, further enhancement of oxidative damage, lipid peroxidation, and glutathione peroxidase 4 expression downregulation are observed for skin tumor cells, validating the synergistic amplification of ferroptosis." (PMID 40387609, 2025).
soft tissue sarcoma (1 paper, 2023). A malignant neoplasm arising from muscle tissue, adipose tissue, blood vessels, fibrous tissue, or other supportive tissues excluding the bones. "According to the CCLE database, high SHARPIN mRNA expression is significantly associated (High vs Middle, p < 0.005; High vs Low, p < 0.05) with high GPX4 dependency in a bone and soft tissue sarcoma cohort." (PMID 37444594, 2023).
spondylitis (1 paper, 2021). The inflammation of a vertebra. "Another study on GPX4 ablation mice showed that GPX4 ablation induced degeneration of spinal cord motor neurons showed the characteristics of ferroptosis, including no caspase-3 activation, no TUNEL staining, ERK activation and elevated spondylitis." (PMID 34922574, 2021).
synucleinopathy (1 paper, 2023). A neurodegenerative disease that is characterized by the abnormal accumulation of aggregates of alpha-synuclein protein in neurons, nerve fibers or glial cells. "Interestingly, in the early stage of PD, synucleinopathy-related lipid peroxidation and GPX4 downregulation occurred preferentially in the midbrain but not in the cortex or hippocampus." (PMID 37183824, 2023).
systemic sclerosis (1 paper, 2025). A chronic disorder, possibly autoimmune, marked by excessive production of collagen which results in hardening and thickening of body tissues. "In systemic sclerosis, GPX4 inhibition significantly reduces fibroblast viability and increases their sensitivity to ferroptosis." (PMID 40883748, 2025).
temporal lobe epilepsy (1 paper, 2025). A localization-related (focal) form of epilepsy characterized by recurrent seizures that arise from foci within the temporal lobe, most commonly from its mesial aspect. "As observed in a Temporal Lobe Epilepsy rat model, Klotho overexpression significantly reduced iron overload, increased glutathione peroxidase-4 (GPX-4) and glutathione (GSH) levels, and decreased reactive oxygen species (ROS) in the hippocampus." (PMID 40351444, 2025).
thyroid tumor (1 paper, 2022). A benign or malignant neoplasm affecting the thyroid gland. "The observed differential mRNA and protein expression levels of GPX4 and TfR1 in vitro may bear clinical relevance when considering factors such as tumor heterogeneity and the wide-ranging therapeutic response of thyroid tumors harboring diverse mutational signatures." (PMID 36371529, 2022). "Future studies are needed to reconcile the underlying differences between tumor tissue and basal PTC cell line GPX4 expression levels and in vitro responses to pharmacologic inhibition of GPX4 within an emulated 3D thyroid tumor microenvironment in vitro and in vivo." (PMID 36371529, 2022).
transient cerebral ischemia (1 paper, 2021). "A transient cerebral ischemia model was established for mice by middle cerebral artery occlusion (MCAO); glutathione peroxidase 4 (GPx4), ACSL4 and cyclooxygenase 2 (COX2) were detected by Western blot, and changes to mitochondria were observed by a transmission electron microscope." (PMID 33889074, 2021).
ulcer (1 paper, 2023). "The expression of FSP1 and GPX4 in ulcer tissues was significantly lower than that in normal tissues." (PMID 38161691, 2023).
varicocele (1 paper, 2024). A condition characterized by the dilated tortuous veins of the spermatic cord with a marked left-sided predominance. "Such events appear to be GPX4-independent in reproductive pathologies such as varicocele and urogenital infections." (PMID 39273059, 2024). "In our study, the decreased level of testosterone concomitant with increased ACSL4 concentration, and similar levels of GPX4, could suggest a GPX4-independent pathway of ferroptosis in the presence of varicocele and urogenital infection." (PMID 39273059, 2024).
vitamin D deficiency (1 paper, 2024). A nutritional condition produced by a deficiency of VITAMIN D in the diet, insufficient production of vitamin D in the skin, inadequate absorption of vitamin D from the diet, or abnormal conversion of vitamin D to its bioactive metabolites. "The current research found that vitamin D deficiency was positively associated with GPX4 reduction and iron parameters elevation among COPD patients." (PMID 39502871, 2024). "Fourth, the mechanism of vitamin D deficiency-evoked GPX4 decrease and ferritin increase was obscure in the current epidemiological study." (PMID 39502871, 2024). "First, this was an epidemiological research, and the causal relationships between vitamin D deficiency with GPX4 reduction and iron parameters elevation were unknown." (PMID 39502871, 2024).